ELN (elastin)
Diseases named in the same sentence as ELN in open-access papers (continued):
Sharing a sentence is not in itself a finding about the gene and the disease.
cancer (continued). "For example, in lung and colon cancer, the degradation of the matrix and fragmentation of elastin was found mainly to occur at the invasive front, and the expression levels of MMP also correlated to the metastatic potential of these cancers." (PMID 37298452, 2023). "LOXL2 belonging to the LOX family, has the typical function of catalyzing the cross-link of elastin and collagen in the ECM and has attracted much attention in cancer biology." (PMID 36185284, 2022). "MMPs cleave a wide range of substrates, such as collagen, FN, laminin and elastin (ELN) and involve in degradation of basement membranes and other ECM barriers, participating in both normal processes and pathogenesis noted in cancer progression." (PMID 35260891, 2022). "This sialidase is not only required for the biological effects that are mediated by the elastin-derived peptides on several metabolic disorders, but NEU-1 is also involved in the development of various cancers." (PMID 36230790, 2022). "Cancer stroma and the extracellular matrix (ECM) are the important factors for cancer progress, including few fibroblasts, mesenchymal cells and collagen, elastin, fibrin, fibronectin, respectively." (PMID 34357224, 2021). "To understand the mechanism of increased ELN in CRC, we measure ELN gene expression in cancer cells after TGF-β stimulation." (PMID 32171282, 2020). "As expected, reduced levels of TIMP3 and elastin (ELN), the major components of elastic fibers, were found in iCCA proteome profiles, while high levels of POSTN were found in all the cancer samples." (PMID 31687002, 2019). "Advanced cancer cells such as CL1-5 cells can secrete lysyl oxidase (LOX), an extracellular copper enzyme that oxidizes lysine residues in elastin and collagen to form covalent cross-linking between these fibrous proteins that can stiffen the matrix." (PMID 27505887, 2017). "MMP-9 are metalloproteases that have been shown to participate in cancer pathogenesis as they degrade type IV collagen, a major component of basement membrane, as well as other types of collagens (V, VII and X), elastin and fibronectin." (PMID 19789535, 2009). "Cancer cells can coax infiltrating fibroblasts to increase their ECM deposition, and the increased presence of lysyl oxidase (LOX) and transglutaminase in the TME results in increased cross-linking between collagen and elastin." (PMID 36765912, 2023). "Similarly, CTSS was previously reported in cancer metastasis for its role of degrading extracellular matrix (ECM) proteins including laminin, fibronectin elastin, osteocalcin and some collagens." (PMID 36803413, 2023). "Given that elastin induces ferroptosis, combining elastin (GSH inhibitor) with cisplatin (genotoxic agent) may have a synergistic effect on cancer therapy." (PMID 37025659, 2023). "No significant red PpIX fluorescence was observed in the cancer stroma, which exhibited bright green AF due to dense connective tissues, such as collagen and elastin, visible in Masson’s trichrome-stained section." (PMID 34253233, 2021). "Elastin is a key protein in the ECM that has not been extensively explored for its potential role in cancer progression." (PMID 34359550, 2021). "The artery markers, Acta2 and Elastin, were significantly up-regulated in response to osteolytic cancer cells, however, not in response to osteoinductive cancer cells." (PMID 29988965, 2018). "As the source of NADH and flavins is primarily cellular, our conclusion is that the progressive decrease in ratios of elastin/NADH and elastin/flavins may reflect adherence, epithelialisation and invasion of tissue by cancer cells." (PMID 27446646, 2016). "The combination of T-stage and elastin-detected VI was at least equivalent to T-stage and nodal status in predicting cancer-specific survival, and superior to TNM in node-negative disease." (PMID 25601902, 2014). "ELN proteins are also increased in cancer cells compared to normal colon epithelial cells." (PMID 32171282, 2020).
cardiovascular disease (41 papers, 2012 to 2025). "With aging, the aorta stiffens due to increased collagen and decreased elastin, thereby increasing the risk of cardiovascular disease." (PMID 38698865, 2024). "Age-related decline in functional elastin is associated with increased arterial stiffness, a known risk factor for developing cardiovascular disease." (PMID 37179824, 2023). "The disorganization or insufficiency and improper assembly, fragmentation, and biochemical modifications of elastin are associated with many cardiovascular diseases." (PMID 36672718, 2023). "Cathepsin K, S, and V have been shown to play a role in cardiovascular diseases by causing excessive elastin degradation." (PMID 35501334, 2022). "In fact, both genetic and acquired cardiovascular diseases are associated with the insufficiency or disorganization of elastin and the breakage of elastic fibers." (PMID 34917605, 2021). "Specifically, cathepsin S has been implicated in elastin degradation in cardiovascular disease, and high levels of cathepsin S have been described in the atheroma plaque." (PMID 33322093, 2020). "While haploinsufficiency of the elastin gene was unambiguously associated with the cardiovascular disease in WBS, the question which other genes are dosage-sensitive and contribute the clinical phenotype still remains unanswered." (PMID 31722427, 2019). "Vascular calcification is a risk predictor and common pathological change in cardiovascular diseases that are associated with elastin degradation and phenotypic transformation of vascular smooth muscle cells via gelatinase matrix metalloproteinase-2 (MMP2)." (PMID 28164126, 2017). "With population studies focused on specific cohorts of individuals diagnosed with cardiovascular disease, opportunities now exist to identify and characterize additional rare genetic variants associated with the elastin gene." (PMID 23049958, 2012). "Animal models provide further evidence for elastin deficiency as the main cause of cardiovascular disease in WBS, underscoring the prominent role of the elastic matrix in the morphogenesis and homeostasis of the vessel wall." (PMID 22319452, 2012). "Furthermore, skin wrinkling at the upper inner arm has been linked to health status and elastin morphology in the PD has been linked to cardiovascular diseases risk." (PMID 26066511, 2015). "Greater PWV, associated with increased risk of cardiovascular diseases, may result from altered expression of the extracellular matrix proteins, collagen and elastin, as well as cross‐linking of proteins by advanced glycation end products (AGEs)." (PMID 24760522, 2014). "This hypothesis is supported by studies linking mutations in elastin with more complex multifactorial manifestations of cardiovascular disease." (PMID 23049958, 2012). "Previous studies have demonstrated a relationship between IL-1β and elastin metabolism in the development of cardiovascular disease." (PMID 39232217, 2024). "The elastin gene seems to account for several comorbidities and distinct clinical features such including cardiovascular disease, connective tissue abnormalities, growth retardation, and gastrointestinal (GI) symptoms." (PMID 37328513, 2023). "Typically, elastin is very stable with a considerably low turnover rate, with degradation or damage indicating pathological remodelling of the tissue and cardiovascular disease." (PMID 37498175, 2023). "Recent studies show promising results for plasma desmosine (pDES), an elastin-specific degradation product, as a marker of cardiovascular disease (CVD) outcomes." (PMID 36479574, 2022). "In this review, we aim to elucidate how the ratios of collagen-I to collagen-III and elastin to collagen are altered in cardiovascular diseases and the aged individuum." (PMID 34421650, 2021). "ECM remodeling and in particular elastin deposition has been previously imaged in vivo in the setting of cardiovascular disease using the gadolinium-based elastin-specific molecular probe ESMA22,23." (PMID 33767303, 2021).
cardiovascular disease (continued). "We determine how the COL1/COL3 and ELN/COL ratios deviate from physiologic baselines in cardiovascular diseases and the aged individuum and identify a continuous scale defining physiological and distinct pathological stages." (PMID 34421650, 2021). "In this review, we specify COL1/COL3, and elastin to total collagen (ELN/COL) ratio-changes in multiple cardiovascular diseases and aging." (PMID 34421650, 2021). "This homeostasis is often accompanied by alterations of elastin expression levels and structures in many cardiovascular diseases." (PMID 34917605, 2021). "To better understand the relationship between elastin and the pathogenesis of cardiovascular diseases, we explored the structure, biosynthesis, and molecular regulation mechanism of elastin." (PMID 34917605, 2021). "Because cardiovascular disease in WBS has been credited to the ELN gene deletion, it is intriguing that at least 15% of the patients with this deletion do not have cardiac abnormalities." (PMID 26090456, 2015). "Elastin insufficiency has well-established consequences for cardiovascular disease, and now our findings demonstrate that elastin levels have implications for metabolic health." (PMID 26167199, 2014). "We therefore speculate that vitamin K might be a potential link between COPD and cardiovascular disease by protecting against systemic elastin degradation through an MGP-dependent pathway." (PMID 36835797, 2023). "Finally, elastin represents a novel promising molecular biomarker also in the field of cardiovascular diseases." (PMID 34827210, 2021). "Moreover, elastin is reportedly involved in the development and progression of many cardiovascular diseases through changes in its expression and structural modifications once deposited in the extracellular matrix." (PMID 34917605, 2021). "The recent findings in the literature using bone marrow-derived stem cells to treat cardiovascular diseases support our hypothesis to use bone marrow-derived OCs to treat vascular elastin-specific calcification." (PMID 34203711, 2021). "Meanwhile, regulation of ERK1/2 activity is associated with cardiovascular disease, and inhibitors decreased ERK1/2 activity and increased aortic elastin content, suggesting the feasibility of ERK1/2 inhibitors in the treatment of AS with reduced arterial elastin content." (PMID 35237603, 2022). "In summary, we found collagen-I relative concentration to increase or stay the same in cardiovascular disease, resulting in a tendency for increased collagen-I/collagen-III and decreased elastin/collagen ratios." (PMID 34421650, 2021). "Coexpression networks showed several key genes in these cardiovascular diseases, for example, KCNK3, TNNI3, and ELN." (PMID 34003819, 2021). "Targeting MPO activity or blocking specific oxidative pathways may help preserve elastin structure and prevent ECM destabilization in cardiovascular diseases." (PMID 41312739, 2025). "All patients in this study had a heterozygous deletion of the ELN gene, and all patients (except for patient No. 9) developed cardiovascular disease, which is consistent with previous reports." (PMID 35379245, 2022). "Given the importance of elastin in the aorta and other elastic arteries, it is not surprising that disorders in elastin production and assembly can result in cardiovascular disease." (PMID 23049958, 2012). "Unfortunately, as demonstrated in this review, COL1/COL3 and ELN/COL ratios in the human heart and aorta remain minimally researched or severely-outdated in literature, leaving a considerable knowledge gap for even some of the most widespread cardiovascular diseases." (PMID 34421650, 2021). "However, as there is virtually no renewal of elastin over the lifetime of adult humans, it may be hypothesized that their molecular aging has a major impact on vessel function and could favor many aspects of cardiovascular diseases." (PMID 34497312, 2021).
infection (41 papers, 2008 to 2025). The state of being infected such as from the introduction of a foreign agent such as serum, vaccine, antigenic substance or organism. "Infection during pregnancy is linked to an increase in surfactant production and a decrease in elastin production at the secondary crests, which are crucial in secondary septum formation." (PMID 40405927, 2025). "Given that humans have been demonstrated to be susceptible to infection by both L. borgspetersenii and L. santarosai and that abraded skin is an exploited point of entry to their hosts, these data implicate elastin as a potential target during zoonotic transmission events." (PMID 38399649, 2024). "Thus, the mutation of elastin a somehow accelerates cardiovascular aging or makes mutant zebrafish more susceptible to infection." (PMID 37408270, 2023). "Genes involved in cell adhesion and structural components, including laminins (LAMA2), elastin (ELN), and collagens (COL16A1, COL13A1, COL8A1) were significantly downregulated at 24 hours post-infection (hpi) in both variants." (PMID 41200555, 2025). "While binding to elastin has been observed with S. aureus, the consequences of this interaction to infection are currently underappreciated." (PMID 38337187, 2024). "Simultaneous to the neutrophil response, monocytes are recruited to the site of infection by hECM proteins, including collagen, fibronectin, serum complement factors, and elastin." (PMID 38337187, 2024). "OmpL37, another surface-exposed protein in Leptospira, demonstrated a higher adhesion affinity for elastin tissue than other outer membrane proteins, suggesting its critical role in the infection process." (PMID 39845041, 2024). "The first step in the infection process is the attachment to host cells or, for example, connective tissue proteins such as collagen, fibrinogen, fibronectin, elastin, or keratin." (PMID 39452228, 2024). "During infection, neutrophil depletion prevents T. brucei-induced collagen and elastin breakdown and thus avoids severe ECM remodeling." (PMID 37669943, 2023). "CflA and FlbPA are essential virulence proteins of S. aureus that adhere to human body proteins, such as elastin, fibronectin, and fibrinogen, during the infection process." (PMID 36830301, 2023). "Extracellular matrix proteins, laminin and elastin genes expression also significantly increased in presence of P2X4 (HCV/P2X4) on day 9 of post-infection compared to control group NV/HCV cells." (PMID 35594248, 2022). "After infection, the proportion of elastin in the lungs increased substantially, and it was more abundant in the serosa." (PMID 36034702, 2022). "A significant increase was observed in levels of ECM markers, elastin and laminin on day 5, 9 of post infection in HCV infected cells in presence of P2X4 than the control NV/HCV cells." (PMID 35594248, 2022). "As seen in S. aureus, the fibronectin binding proteins FnbpA and FnbpB recognize fibronectin, fibrinogen, and elastin, which can facilitate the establishment of an infection by the microbe in a variety of host species and tissue types." (PMID 33055259, 2020). "These two exoenzymes greatly influence the pathogenicity of P. aeruginosa, contributing to infection establishment through elastin degradation and vascular permeability, respectively." (PMID 33262953, 2020). "FnBPA and FnBPB play a crucial role in binding to components of the host extracellular matrix proteins fibronectin, fibrinogen, and elastin, an important mechanism for colonisation of host tissues during infection." (PMID 30153881, 2018). "Nevertheless, OmpL47 is reported to be a surface exposed protein that binds skin and elastin and is expressed during infection." (PMID 28848720, 2017). "Next to confirm expression of the elastin gene, BMSCs infected with Ad-CMV-elastin-GFP were harvested 24 hours after infection." (PMID 27048404, 2016).
infection (continued). "During the initial stage of infection, the strong binding affinity of OmpL37 for human skin elastin would facilitate the attachment of leptospires to an inner elastin-rich layer of the skin exposed by abrasion." (PMID 20844573, 2010). "The presence of elastin fiber (EF), a marker of parenchymal lung destruction, in tracheal secretion has been proposed to differentiate colonization from infection of the lung." (PMID 18426596, 2008). "As observed with Leptospira sp., elastase expression appears to promote infection by degrading dermal elastin, which may act as a barrier to microbial infiltration." (PMID 37001705, 2023). "Leptospira binding to dermal elastin may represent a key first step in establishment of infection, as exposed dermal elastin would be present within open wounds." (PMID 37001705, 2023). "The necessity of a two-stage procedure, high risk of infection, inconsistent long-term results, absence of elastin and the huge financial burden are the most reported drawbacks and are therefore important limiting factors for general use." (PMID 37143955, 2023). "Furthermore, collagen-I and elastin were found to be up-regulated and concentrated in the pleura at the mRNA and protein levels following infection." (PMID 36034702, 2022). "This work aimed to assess the transcriptional profile of T. rubrum grown on different protein sources (keratin or elastin) to mimic natural infection sites and exposed to trans-chalcone in order to elucidate the mechanisms underlying the antifungal activity of trans-chalcone." (PMID 31117938, 2019). "Thus it is also possible that maintenance of a free binding site in N2N3 results in targeting of bacteria to elastin-rich tissues such as blood vessel walls during the initiation of infection." (PMID 24627488, 2014). "Indeed, OmpL37 binding and leptospiral attachment to elastin are both enhanced by OmpL37 antiserum, further implicating a possible role for OmpL37 during infection." (PMID 20844573, 2010). "Since the production of collagens, elastin and clusterin play an essential role in fibrotic responses after tissue injury, these results indicate that sub-lethal infection with CoV2 induces a chronic inflammatory response and may mediate fibrosis in the lungs of K18 mice at 21 DPI." (PMID 38092883, 2023). "Interestingly, elastase inhibition improves the effectiveness of alum adjuvants in SARS-CoV-2 vaccines to promote resolving systemic and mucosal immunity indicating that elastin degradation may critically alter immune responses during infection." (PMID 37001705, 2023). "Mice, retaining infection with AA43 and AA44 CF-adapted variants for one month, displayed hallmarks of CF chronic lung pathology: intraluminal and peribronchial inflammation, epithelial hyperplasia and structure degeneration, goblet cell metaplasia, collagen deposition and elastin degradation." (PMID 26883959, 2016). "In addition, the binding to repair proteins, such as fibroblastic fibronectin, type III collagen, and elastin, following the initial hemostasis could occur away from circulating antibodies raised either in a previous infection or by vaccination." (PMID 21347378, 2011). "Cathepsins and neutrophils both contribute to the presence of secretory granules during infection, however CTSL can also break down lung elastin that can also lead to tissue damage." (PMID 33187194, 2020). "These loci exhibited negative (ELN, SASH1, and SMAD7) and positive (CDSN, NCSTN, and PEX7) relationships between minor allele frequency and infection severity, with no overarching pattern evident in control loci lacking association with mange severity." (PMID 33664786, 2021). "A similar pattern of elastin degradation was found in BALF of patients with exacerbation of an ILD without infection but with evidence of aspiration of gastric contents." (PMID 30170599, 2018).
infection (continued). "We found that ELN did not protect macaques from SHIV acquisition although it reduced the SHIV-induced inflammatory status during the acute phase of infection." (PMID 27348748, 2016).